C1QA (complement C1q A chain)
Diseases named in the same sentence as C1QA in open-access papers (continued):
Sharing a sentence is not in itself a finding about the gene and the disease.
ischaemic stroke (1 paper, 2021). "We detected the specific expression of C1QA and Casp14 in the EVs of patients with CSC ischaemic stroke and the specific expression of ANXA2 in the EVs of patients with SC involvement." (PMID 34356850, 2021). "C1QA, FGG, FN1, and VWF could therefore be involved in atherogenesis progression in patients with CSC ischaemic stroke." (PMID 34356850, 2021).
keloid (1 paper, 2022). An irregularly shaped, elevated mark on the skin caused by deposits of excessive amounts of collagen during wound healing. "Furthermore, two modules of macrophages (Module2: highly expresses RNASE1, C1QA, CD163, CD14, C1QC, FCGRT, and MS4A7; Module10: highly expresses APOC1, CTSB, CTSL, and TYROBP), which exhibited the characteristics of TAMs, increased significantly in keloid." (PMID 35990663, 2022).
kidney cancer (1 paper, 2020). Primary or metastatic malignant neoplasm involving the kidney. "In particular, for the first time we have shown the importance of the C1QA gene in the development of kidney cancer." (PMID 31936274, 2020).
liver disease (1 paper, 2025). "We then selected three of the top upregulated or downregulated genes in aging for further studies in liver diseases/cancer: B2M (upregulated with age), C1qA (upregulated with age), and SUCLG1 (downregulated with age)." (PMID 39941711, 2025). "While B2M and C1qA did not display any change across the spectrum of liver disease, SUCGL1 mRNA expression decreases significantly and progressively with the deterioration of liver disease, reaching the lowest levels in malignant settings, i.e., HCC and CC." (PMID 39941711, 2025).
muscular dystrophy (1 paper, 2011). Muscular dystrophy (MD) refers to a group of more than 30 genetic diseases characterized by progressive weakness and degeneration of the skeletal muscles that control movement. "C1S, C3 and C1QA genes, involved in complement mediated immunity contributing to muscular dystrophy, also showed heterogeneous expression across the dystrophy samples, with corresponding changes in tm-scores." (PMID 21453538, 2011).
nasal polyps (1 paper, 2022). "C1QA and C1QB are the components of complement C1q, the expression of which was significantly increased in nasal polyps according to a previous study." (PMID 36466903, 2022).
ovarian tumors (1 paper, 2023). "Multicolor imaging data further confirmed the coexistence of monocyte-derived M07 EREG+ macro and RTM-derived M10 C1QA+ macro in ovarian tumors." (PMID 37488416, 2023).
pancreatic NET (1 paper, 2023). "The selection of C1QA and COMP as the preferred biomarkers implies that these proteins strongly associate with pancreatic NET and hold promise as indicators for early disease detection." (PMID 38030709, 2023).
pleural tumors (1 paper, 2024). "Compared with C1qafl/fl mice (also denoted as fl/fl in the text), C1qa CKO mice exhibited reduced volume of MPE, decreased weight of pleural tumors, and extended time of survival, consistent with findings from C1qa globally KO mouse MPE models." (PMID 39664577, 2024). "To provide a comprehensive interpretation of C1q-mediated immune responses during MPE formation, we collected MPE and pleural tumors from C1qa-/- and WT mice, isolated mononucleated cells, and proceeded with scRNA-seq using the Singleron platform." (PMID 39664577, 2024). "The results demonstrated a reduced volume of MPE volume and smaller mass of pleural tumors in C1qa-/- mice compared to WT ones." (PMID 39664577, 2024). "Our results demonstrate that both global C1q deficiency and macrophage-specific C1q deficiency can reduce MPE volume, inhibit pleural tumor growth, and prolong mouse survival, with no significant survival difference observed between the C1qa-/- and C1qa CKO mice." (PMID 39664577, 2024). "In C1qa-/- mice, NK cells displayed a phenotype characterized by increased effector-like features and decreased exhausted features in both MPE and pleural tumor cells." (PMID 39664577, 2024). "The scRNA-seq data also demonstrated that CD4+ T cells from C1qa-/- mice had a phenotype with enhanced helper-like features, while CD8+ T cells displayed a phenotype with increased effector-like characteristics and decreased exhaustion in both MPE and pleural tumor cells." (PMID 39664577, 2024).
preeclampsia (1 paper, 2021). Preeclampsia is a hypertensive disorder of pregnancy that is characterized by new-onset hypertension with proteinuria presenting after 20 weeks of gestation, and depending on mild or severe forms may initially present with severe headache, visual disturbances, and hyperreflexia. "Additionally, complement-associated genes were reduced in early-onset preeclampsia compared to healthy placentas (P=0.007), including complement 7 (C7), complement C1q A chain (C1QA), complement 2 (C2), and complement C1r (C1R)." (PMID 34992598, 2021). "M2 macrophages (CD136+MRC1+C1QA+C1QB+, P=0.007) and mast cells (TPSAB1, P=0.007) were decreased in early-onset preeclampsia samples, while M1 macrophages (CD86+MSR1+) were not altered based on gene expression." (PMID 34992598, 2021).
renal fibrosis (1 paper, 2023). A final common manifestation of a wide variety of chronic kidney diseases characterized by glomerulosclerosis and tubulointerstitial fibrosis. "Moreover, the observed alterations in the mRNA expression of C1QA and C1QC genes could also be a secondary treatment effect, means secondary to primary effects of empagliflozin on for example renal fibrosis." (PMID 36779666, 2023).
retinal ischemia (1 paper, 2016). A ischemic disease that involves the retina. "Here we compare the effects of a retinal ischemia/reperfusion (I/R) injury on glial activation and neurodegeneration in wild type (WT) and C1qa-deficient mice in the retina and superior colliculus (SC)." (PMID 27008854, 2016).
schistosomiasis (1 paper, 2021). An infectious disease caused by parasitic trematodes of the genus Schistosoma that colonize human blood vessels and release eggs that can cause granulomatous reactions leading to acute (swimmer's itch or acute schistosomiasis syndrome) or chronic disease. "Based on the hierarchal clustering analysis results and key modulated signalling pathways, the proteins complement C1q subcomponent subunit A (C1QA, 1.82-fold) and complement factor D (CFD, 2.51-fold) were differentially expressed in the SHF-F4 and SHF-F2 groups of schistosomiasis patients." (PMID 33933138, 2021).
steatosis (1 paper, 2022). Increased lipid within the cytoplasm of cells. "The expression of C1qa, C1qb, C1qc, and C2 in KCs was significantly higher in patients with severe steatosis when compared to healthy controls." (PMID 36304458, 2022). "KCs in healthy and steatosis patients highly expressed C1qa, C1qb, C1qc, and ApoE transcripts." (PMID 36304458, 2022).
temporal lobe epilepsy (1 paper, 2015). A localization-related (focal) form of epilepsy characterized by recurrent seizures that arise from foci within the temporal lobe, most commonly from its mesial aspect. "However, activation of the complement system, i.e. upregulation of complement mediators including C1qa and C1r, has been reported in both experimental and human temporal lobe epilepsy and is thought to contribute to neuronal hyper-excitability and seizures." (PMID 26684451, 2015).
Wiskott-Aldrich syndrome (1 paper, 2017). Wiskott-Aldrich syndrome (WAS) is a primary immunodeficiency disease characterized by microthrombocytopenia, eczema, infections and an increased risk for autoimmune manifestations and malignancies. "These genes, namely, Complement C1q A Chain (C1QA), Fc Fragment Of IgE Receptor Ig (FCER1G) Vav Guanine Nucleotide Exchange Factor 1 (VAV1) and Wiskott-Aldrich Syndrome (WAS) were all confirmed to be significantly upregulated." (PMID 29232382, 2017).
tumor (83 papers, 2013 to 2026). "scRNA-seq and scTCR-seq analysis show that cKO mice exhibit reduced immunosuppressive Ms4a7+C1qa+ tumor-associated macrophages (TAMs) but increased intratumoral IFN-γ+CD8+ T cell infiltration and expansion." (PMID 41431992, 2025). "Genes such as APOE, TREM2, VENTX, and C1QA are associated with tumor growth and progression, promotion of apoptosis, and inflammation." (PMID 38910324, 2024). "Among macrophages, most cells expressed high levels of complement (C1qa, C1qb, C1qc), which in tumor-associated macrophages have been reported to correlate with immune exhaustion and poor survival." (PMID 36433954, 2022). "While cluster 2 highly expressed C1qa/C1qc genes that were found upregulated in a previously reported M2-like tumor associated macrophage cluster." (PMID 35260564, 2022). "Cells in Mac_0 were characterized by expression of complement-related genes (C1qa, C1qb, C1qc) and cytokines (Spp1, Ccl12), while cells in Mac_1 expressed higher levels of several tumor-associated macrophage-related genes such as Arg1, Cebpb, and Ier3." (PMID 34030676, 2021). "Macrophages in HCC are tumor associated macrophages (TAMs), based on marker genes C1QA, C1QB, co-express M1, and M2 signals (e.g. M1:CD64, M2: MACRO)." (PMID 33224891, 2020). "C1QA encodes the A-chain polypeptide of complement subcomponent C1q and plays an important role in counteracting tumour cells." (PMID 31381571, 2019). "Blood monocytes and tumor-associated macrophages also expressed C1qA and may affect tumor cells through it." (PMID 37907575, 2023). "C1q-deficient (C1qa−/−) mice, bearing a syngeneic B16 melanoma, exhibited slower tumor growth and prolonged survival, compared to C3 or C5 deficient mice although it has been shown that C3/C5 deficiency may also create microenvironment suboptimal for tumor growth." (PMID 31130944, 2019). "Complement components C1qA, C1qB, and C1qC were significantly increased in tumor-bearing mice that had been irradiated, whereas similarly aged mice without tumors displayed a decline in complement system activity." (PMID 40757647, 2025). "Cell–cell communication analysis suggested C1QA interacts with neutrophils via complement receptors, contributing to an immunosuppressive tumour microenvironment." (PMID 41171372, 2025). "C1q is a complement protein produced by tissue-resident macrophages, and macrophages that coexpress both C1qa and Apoe represent a tumor-supporting, prometastatic population." (PMID 38717149, 2024). "Utilizing C1qa KO mice, the data demonstrate that C1q deficiency in macrophages suppresses MPE, inhibits tumor growth, and prolongs murine survival." (PMID 39664577, 2024). "Upregulated cathepsin activity (CTSB, CTSD, and CTSZ) and complement pathway (C1QA, C1S) indicated pro-tumor activity by the TAMs in this region." (PMID 38217035, 2024). "Recent evidence suggested that C1qA, C1qB, C1qC positively influence anti-tumor through antibody-mediated immune responses." (PMID 39232806, 2024). "For the mouse liver cell dataset, gene C1qa is a commonly used biomarker, and the high expression of C1qa has been identified as a tumour-specific signature." (PMID 37697330, 2023). "When compared to the R-Vector group, the levels of C1qA expression and the complement system proteins in tumor tissues from the R-C1qA group were increased." (PMID 37907575, 2023). "Collectively, these findings indicated that METTL3 was a writer for C1qA methylation that inhibited the activity of the complement system and thus promoted tumor cell proliferation both in vitro and in vivo." (PMID 37907575, 2023). "Our previous study reported that macrophages from a tumor or metastatic LNs can be defined as C1QA+ macrophages, which had a dominant M2-like phenotype and immunosuppressive function." (PMID 36569924, 2022). "C1QA is produced in the tumor microenvironment and functions as an extracellular matrix protein, promoting tumor growth and metastasis." (PMID 35368886, 2022).
tumor (continued). "C1Q Macros expressed C1QA/B/C genes similarly to MAFB+ LC, but uniquely expressed FCGR3A and were enriched in a C1Q tumor-associated macrophage (TAM) gene-set." (PMID 36741389, 2022). "In the endometrial macrophages, the most significantly expressed genes were C1qa and C1qc, components of the C1q complex of the complement system which can also act as a tumor-promoting factor." (PMID 36424602, 2022). "Immune and stromal cell populations included 2 populations: Macrophages 1 (c1: C1qa, C1qb, C3aR1, Cd68, Csf1r, Tlr2, and Cd86) and 2 (c6 + c9: Ccr7, Csf2rb, Il1b, and Cd74) expanded in PNs as a percentage of total tumor cells." (PMID 36134665, 2022). "Among them, Module2 (highly express RNASE1, C1QA, CD163, CD14, C1QC, FCGRT, and MS4A7) and Module10 (highly express APOC1, CTSB, CTSL, and TYROBP) are more likely to display the characteristics of tumor-associated macrophages (TAMs)." (PMID 35990663, 2022). "Immunofluorescence results showed that C1QA expression in tumor, P-LN, and N-LN was higher, while MRC1 in P-LN was higher than that in tumor and N-LN." (PMID 36569924, 2022). "Similar to the SAMs, the TAMs in the primary tumor separated into two populations: one with high expression of Chil3, Plac8, and Ly6c2 (Chil-TAMs), and the other with high expression of C1qa, C1qb, and Trem2 (Cq-TAMs)." (PMID 33782087, 2021). "Taken together, we detected an increase in Cq-TAMs and an increase in the expression of Chil3, Trem2, C1qa, and C1qb in the tumor compared with the normal pancreas." (PMID 33782087, 2021). "Compared with other immune cells, the macrophages in the primary tumor (i.e., TAMs) exclusively exhibited high expression of the SAMs signature genes (Chil3, Trem2, C1qa, and C1qb), whereas Plac8 and Ly6c2 were broadly expressed across cell types." (PMID 33782087, 2021). "To find new potential checkpoints, we investigated the cell-cell communications between tumor-promoting immune cells (CD4_CXCL13, CD4_FOXP3, CD8_CXCL13, CD8_ISG15, Mac_C1QA, Mac_ISG15, Mac_SPP1 and cDC3_LAMP3) and the ductal epithelial cells." (PMID 35087839, 2021). "Similar to our scaffold and primary tumor data, the macrophages in the liver metastases had high expression of C1QA, C1QB, and TREM2 consistent with this macrophage population being part of a systemic response to a primary tumor." (PMID 33782087, 2021). "C1QA can act independently of the complement system as a cancer-promoting factor in the tumor microenvironment." (PMID 33488671, 2020). "Syngeneic reconstituted C1qa−/− mice and chimeric mice becoming C1q sufficient after BM transplantation developed smaller tumours." (PMID 26831747, 2016). "Conversely, WT mice reconstituted with C1qa−/− BM cells and syngeneic reconstituted WT mice showed accelerated tumour growth." (PMID 26831747, 2016). "We found that the vascular density in tumour-bearing WT mice was significantly higher than in C1qa−/− animals, particularly in the peri-tumoral area." (PMID 26831747, 2016). "The majority of these are tumor-derived, although several host proteins (C1qa, C1qc and Vwf) are also identified as being downstream of TGFβ." (PMID 24618895, 2014). "In addition, the up-regulation of C1qb, C1qa, Lamp1, Lgals3, Gm2a, Gusb, Bax, and other genes helps to enhance the anti-tumor and anti-infection ability of the immune system." (PMID 40767963, 2025). "Furthermore, APOE, APOC1, C1QA, C1QB, and NUPR1 are indicative markers of variations in the infiltration of tumor-associated macrophages (TAM), where TAM infiltration is known to be associated with unfavorable survival outcomes in solid tumors." (PMID 38783355, 2024). "In both MPE and tumor tissues, C1qa was primarily expressed in macrophages." (PMID 39664577, 2024). "C1QA is expressed in the stroma and vascular endothelium of several human malignant tumors and its downregulation results in improved therapeutic control by controlling tumor metastasis." (PMID 38910324, 2024).
tumor (continued). "In addition, when compared to the S-shCtrl group, the levels of C1qA expression and complement system proteins in tumor tissues from the S-shC1qA group were suppressed." (PMID 37907575, 2023). "We observed that tumor-associated macrophages highly expressing C1QC, C1QA, and C1QB could be identified as C1QC + macrophages." (PMID 37344903, 2023). "In addition, multiple components of the complement system, a central mediator of RT-induced tumor-specific immunity, were upregulated — specifically, C1qa, C1qb, C1ra, C1s1, C3, C3ar1, C4b, and C6." (PMID 37345658, 2023). "We found that the mRNA expression of C1QA, C1QB, C1QC, C5AR1, C3AR1, C1QR (CD93), CR1, CR2, CR3 (ITGAM), and CR4 (ITGAX) were positively associated with almost all kinds of tumor immune cells, including CD8+ T cells, CD4+ T cells, B cells, macrophages, monocytes and DCs." (PMID 34813686, 2022). "Similarly, analysis of macrophages from the 3 states revealed that there were distinct genes in the Tumor macrophages which includes genes like Cotl1, Tgfbi, Fos, and Fn1 along with complement activation genes C1qa, C1qb, and C1qc." (PMID 35851387, 2022). "Prior work has shown how sub-units of the C1Q complex, including C1QA, C1QB, and C1QC, are associated with modulating the local environment of tumor cells and may therefore reflect local microenvironment remodeling after brain injury." (PMID 36670596, 2022). "Having identified Chil3, Trem2, and the complement genes, C1qa and C1qb as markers of SAMs in tumor-bearing mice, we next investigated whether these macrophage subsets also exist in primary tumors." (PMID 33782087, 2021). "Therefore, C1qA, C1qB and C1qC differential expression is closely related to the degree of tumor necrosis, plays a role in inhibiting tumor development to a certain extent." (PMID 34079754, 2021). "In addition, high C1QA expression was associated with poor prognosis in early-stage LUAD patients (Stages I–II) based on KM plotter analysis, further emphasising the critical role of this gene in tumour progression." (PMID 41171372, 2025). "Of note, C1qA may originate from other non-tumor cells in DLBCL tissue." (PMID 37907575, 2023). "Among potential eat-me signals, we found significant overexpression of C1Q complement components C1qa, C1qb, and C1qc, which have been shown to decorate the surface of apoptotic cells to target them for phagocytosis, and of Slamf7, which is involved in phagocytosis of hematopoietic tumor cells." (PMID 36240276, 2022). "Tumor-associated myeloid cells exhibited higher transcriptional expression of molecules linked to the “find me” (G2A), “eat me” (CD93, TIM1, SCARF1, SLC2A1, GAS6, TREM2, AXL, C1QA), and downstream processing (NR1H3, ATG7, PPARG, ABCA1, PPARD, DOCK180) phases of efferocytosis." (PMID 36439171, 2022). "In addition, tumor-bearing SAMs displayed a high expression of complement C1q A chain and B chain (C1qa and C1qb) and triggering receptor expressed on myeloid cells 2 (Trem2), and a low expression of the major histocompatibility complexes (Cd74, H2-D1, H2-Aa, and H2-Eb1) compared with control SAMs." (PMID 33782087, 2021). "Highly expressed characteristic genes such as C1QA and APOE.The expression of M2 macrophage marker genes in MS4A4A+ TAMs within tumor samples is significantly higher than that in normal tissues, indicating an immunosuppressive role." (PMID 40191203, 2025). "MФ‐C1q expresses C1QA, C1QB and in either tumours or normal tissues, complement C1q is the marker of immunosuppressive macrophages." (PMID 39968688, 2025). "Taken together, the ratio between CD8A and either C1QA, C1QB or C1QC in bulk tumour gene expression data is prognostic in at least five tumour types." (PMID 36724681, 2023). "Comparison of the gene expression of TREM2+ TAMs between the tumor and adjacent normal tissue revealed that TREM2, SPP1, APOE, C1QA, C1QB, and C1QC were upregulated in tumors, which was consistent with the results for GSE160269." (PMID 37187751, 2023).